GCGR (glucagon receptor)
Diseases named in the same sentence as GCGR in open-access papers (continued):
Sharing a sentence is not in itself a finding about the gene and the disease.
liver cancer (2 papers, 2022 to 2023). An epithelial or non-epithelial malignant neoplasm that arises from the liver. "We performed coimmunoprecipitation experiments in HEPG2 human liver cancer cell lines that were transfected with human glucagon receptor-GFP + human ARRDC4-FLAG or glucagon receptor + empty vector controls and treated with glucagon or PBS." (PMID 37451484, 2023). "Similar to the gluconeogenic enzymes, GCGR is also significantly downregulated at the mRNA level in both liver cancer patient samples and cell lines." (PMID 35123542, 2022). "However, whereas our findings support the anti-tumorigenic role of glucagon and GCGR in one model of liver cancer, we were unable to detect increases in gluconeogenic gene expression." (PMID 35123542, 2022). "We hypothesize this could be due to increased levels of the transcription factor, carbohydrate-responsive element-binding protein (ChREBP), in liver cancer that has been shown to positively regulate GCGR expression in rat hepatocytes." (PMID 35123542, 2022). "For the first time, we report a potential tumor suppressive role for glucagon/GCGR in liver cancer." (PMID 35123542, 2022). "Since gluconeogenesis biochemically opposes glucose catabolism, we hypothesized that glucagon signaling would have a tumor suppressive effect in liver cancer cells that are responsive to glucagon, especially if they express sufficient levels of GCGR and key gluconeogenic enzymes." (PMID 35123542, 2022). "Collectively, our data indicate that glucagon cannot induce a uniform augmentation in gluconeogenic gene expression in liver cancer cell lines and that SNU398 cells are most responsive to glucagon upon GCGR overexpression, in terms of downstream signaling." (PMID 35123542, 2022). "The glucagon receptor, GCGR, was overexpressed in liver cancer cell lines consisting of a range of etiologies and genetic backgrounds." (PMID 35123542, 2022). "The mRNA expression of GCGR, G6PC, FBP1, and PCK1 are decreased in patient tumors and heavily silenced in many established liver cancer cell lines." (PMID 35123542, 2022). "Of note, we did not observe a decrease in GCGR expression with glucagon treatment in SNU398 or other liver cancer cell lines, but rather a consistent increase." (PMID 35123542, 2022). "We tested this phenotype in numerous other liver cancer cell lines for glucagon/GCGR robustness but did not measure equivalent changes in cell number compared to SNU398 at 100 nM glucagon." (PMID 35123542, 2022). "It seems possible that a subset of patients with sufficient GCGR and gluconeogenic enzyme accumulation might be candidates for this strategy, but most liver cancer patients would not." (PMID 35123542, 2022). "Therefore, future studies on glucagon signaling in liver cancer could analyze metabolomics profiling of SNU398 GCGR cells with or without glucagon, compared to a cell line that is unresponsive, regardless of glucagon treatment." (PMID 35123542, 2022).
adenoma (1 paper, 2021). A neoplasm arising from the epithelium. "Additionally, six weeks post AOM injection the number of adenomas was unaffected by the missing glucagon receptor expression." (PMID 34108943, 2021). "Disruption of glucagon receptor signaling did not affect body weight during AOM/DSS treatment, neither did it affect the inflammatory score assessed during colonoscopy or the number of large and small adenomas present at the end of the study period." (PMID 34108943, 2021).
all (1 paper, 2025). "We aimed to explore whether changes in GCGR signaling, induced by genetic alterations in the gene that codes for the GCGR, are associated with to cognitive decline or an increased prevalence of all-cause dementia in humans." (PMID 40271226, 2025).
Arrhythmia (1 paper, 2026). Any cardiac rhythm other than the normal sinus rhythm. "However, their development has been challenged by deleterious cardiovascular (CV) effects, including increased heart rate (HR), elongated QTc, and arrhythmia mediated by GcgR agonism." (PMID 41654015, 2026).
asthma (1 paper, 2019). "Since all these inflammatory cells express GcgR, our data indicate that those seem to be crucial cell targets in asthma pathophysiology which are modulable by glucagon." (PMID 31019244, 2019).
atrial fibrillation (1 paper, 2026). A disorder characterized by an electrocardiographic finding of a supraventricular arrhythmia characterized by the replacement of consistent P waves by rapid oscillations or fibrillatory waves that vary in size, shape and timing and are accompanied by an irregular ventricular response. "Therapeutic interventions promoting lymphangiogenesis, either through VEGFC administration or weight loss intervention by LY3437943 (the novel triple GIP, GLP-1, and glucagon receptor agonist), significantly attenuate atrial fibrillation inducibility." (PMID 42156758, 2026).
Cirrhosis (1 paper, 2023). A chronic disorder of the liver in which liver tissue becomes scarred and is partially replaced by regenerative nodules and fibrotic tissue resulting in loss of liver function. "The finding of hyperglucagonemia in patients with cirrhosis has been described in several studies and proposed to be related to impaired glucagon receptor signaling in the liver." (PMID 37078380, 2023).
cognitive decline (1 paper, 2025). "Further research is needed to elucidate mechanisms underlying the potential link between altered GCGR signaling and cognitive decline." (PMID 40271226, 2025). "The GCGR has been reported in hypothalamic nuclei in rats, but a thorough mapping of the GCGR in the human brain and its potential association with cognitive decline has not previously been investigated." (PMID 40271226, 2025).
colon cancer (1 paper, 2018). "Glucagon significantly promoted colon cancer cell growth, and GCGR knockdown with small interfering RNA attenuated the proliferation-promoting effect of glucagon on colon cancer cells." (PMID 29535833, 2018). "In the present study, glucagon suppressed the phosphorylation of AMPK at Thr172 in colon cancer cells through activation of the GCGR pathway." (PMID 29535833, 2018). "In this study, GCGR mRNA and protein expression were demonstrated in colon cancer cell lines by RT-PCR and western blotting respectively, and immunohistochemical staining showed GCGR expression in colon cancer tissue." (PMID 29535833, 2018). "In the current study, expression of GCGR in colon cancer cell lines and colon cancer tissue obtained from patients was demonstrated." (PMID 29535833, 2018). "The effect of glucagon on GCGR-mediated signaling pathways was investigated using mouse colon cancer cell lines CMT93 and CT26." (PMID 29535833, 2018). "To determine whether glucagon is functional in GCGR expressing colon cancer cell lines, we measured intracellular cAMP concentrations in HT29 and SW480 with or without glucagon stimulation." (PMID 29535833, 2018). "Immunohistochemical staining showed that GCGR was expressed in colon cancer tissue." (PMID 29535833, 2018). "In conclusion, GCGR expression was detected in colon cancer tissues obtained from patients." (PMID 29535833, 2018). "Moreover, glucagon was demonstrated to promote colon cancer cell proliferation through binding to GCGR expressed in human and mouse colon cancer cell lines." (PMID 29535833, 2018). "The expression of GCGR was evaluated in human colon cancer tissues obtained from patients." (PMID 29535833, 2018). "Furthermore, to identify the mechanisms promoting colon cancer cell growth by glucagon, the activation of downstream signals of GCGR was examined by western blotting using colon cancer cells treated with glucagon." (PMID 29535833, 2018). "Additionally, GCGR-mediated signals involving colon cancer cell growth were investigated to elucidate the mechanism of how glucagon regulates cancer cell growth." (PMID 29535833, 2018). "It was also shown that downstream signals of GCGR, including AMPK and MAPK pathways, play a crucial role in colon cancer proliferation in vitro and in vivo." (PMID 29535833, 2018). "Besides that, glucagon was found to enhance colon cancer cell proliferation, whereas glucagon did not promote cell proliferation in GCGR knockdown colon cancer cells." (PMID 29535833, 2018). "In the current study, glucagon was found to increase phosphorylation of ERK1/2 in colon cancer cells, and glucagon did not phosphorylate ERK1/2 in GCGR knockdown colon cancer cells, resulting in attenuation of the promoting effect of glucagon on cell growth." (PMID 29535833, 2018).
dementia (1 paper, 2025). Loss of intellectual abilities interfering with an individual's social and occupational functions. "GCGR variant carriers did not have a significantly higher prevalence of dementia, but 1 cognitive test was significantly impaired in individuals with a GCGR cAMP loss-of-function variant compared to sex- and age-matched nonvariant carrier controls." (PMID 40271226, 2025). "Here we aimed to characterize glucagon receptor (GCGR) expression in brain tissue and investigate the potential impact of altered GCGR signaling on dementia prevalence and cognitive function." (PMID 40271226, 2025).
diabetic cardiomyopathy (1 paper, 2023). Diabetic cardiomyopathy is a disorder of the heart muscle in people with diabetes. "We aimed to investigate whether a glucagon receptor (GCGR) monoclonal antibody (mAb) ameliorated diabetic cardiomyopathy and clarify whether and how CMECs participated in the process." (PMID 37596940, 2023). "Our findings might provide a rationale for the future clinical development of GCGR mAb in the prevention and treatment of diabetic cardiomyopathy." (PMID 37596940, 2023).
diabetic kidney disease (1 paper, 2024). Progressive kidney disorder caused by vascular damage to the glomerular capillaries, in patients with diabetes mellitus. "NEW & NOTEWORTHY This study suggests that the glucagon receptor is a potential therapeutic target in the treatment of diabetic kidney disease." (PMID 39265079, 2024). "Here, we investigated whether long-term increased plasma levels of glucagon contribute to the pathophysiological changes seen in diabetic nephropathy, using mouse models of long-term activation and inactivation of glucagon receptor signaling." (PMID 39265079, 2024).
dysplasia (1 paper, 2024). A usually neoplastic transformation of the cell, associated with altered architectural tissue patterns. "In GCGR -/- mice, the progression from pancreatic endocrine cell mass expansion with ACH to dysplasia at 5 to 7 months, proceeding to pNETs < 1 mm at 12 months and then to pNETs > 1 mm at 18 months is well-established." (PMID 39309109, 2024).
hyperplasia (1 paper, 2013). An abnormal increase in the number of cells in an organ or a tissue with consequent enlargement. "Hyperplasia of α-cells has been documented in various mouse models that have defective glucagon action, such those deficient in glucagon receptor or in prohormone convertase 2 that excise glucagon from its precursor proglucagon." (PMID 23671715, 2013).
hypogonadism (1 paper, 2020). A disorder characterized by decreased function of the gonads. "Consequently, if glucagon receptor agonism has a direct effect on the reproductive system (in addition to its metabolic effects), this would be highly clinically relevant because hypogonadism worsens insulin resistance, facilitates weight gain, impairs fertility, and worsens quality of life." (PMID 32232363, 2020).
hypothyroidism (1 paper, 2023). Abnormally low levels of thyroid hormone. "Hence, there is a clear need to also measure in protein levels the expressional changes alluded to above for the glucagon receptor, for example, in hypothyroidism or after prolonged β-adrenergic stimulation, to confirm or refute this earlier work." (PMID 37629010, 2023).
lipid metabolic disorders (1 paper, 2021). "Mice with GCGR dysfunction could not dispose KAA well, resulting in KAA accumulation and lipid metabolic disorders." (PMID 34002801, 2021).
myopia (1 paper, 2025). "Experimental studies using animal models have demonstrated that increasing glucagon levels or enhancing glucagon receptor signaling can reduce myopia progression." (PMID 40933557, 2025).
neuroendocrine tumors (1 paper, 2020). "Dysregulated GCGR trafficking has been linked with hyperglucagonemia and the development of pancreatic α-cell hyperplasia and neuroendocrine tumors." (PMID 32967969, 2020). "We propose that compounds that modulate the deubiquitinase activity of either USP33 or STAMBP may be of therapeutic use in the treatment of neuroendocrine tumors that result from impaired GCGR trafficking and signaling." (PMID 32967969, 2020).
pancreatic adenocarcinoma (1 paper, 2024). "While pathways that stimulate acinar cell expansion could also increase the risk of pancreatic adenocarcinoma, an increased incidence of acinar cell cancers has not been reported in GCGR-deficient patients and animal models." (PMID 39720531, 2024).
papillary thyroid carcinoma (1 paper, 2020). "Consistent with evidence that reduction of glucagon receptor, GCGR, in papillary thyroid carcinoma resulted in the inactivation of EMT and P38/ERK pathways, GCGR was down-regulated in LSCC and may serve as a potential prognostic biomarker and therapeutic target for LSCC." (PMID 33005178, 2020).
renal fibrosis (1 paper, 2025). A final common manifestation of a wide variety of chronic kidney diseases characterized by glomerulosclerosis and tubulointerstitial fibrosis. "However, studies on the effects of GCGR or GLP-1R agonists on renal fibrosis and ER are still limited." (PMID 41280890, 2025). "In this study, our results demonstrated that dual GLP-1R and GCGR agonist TB001 could significantly ameliorate renal fibrosis in UUO mouse models and in vitro cell culture systems." (PMID 41280890, 2025). "Similar to this study, our data showed that the novel GCGR/GLP-1R dual agonists TB001 could ameliorate renal fibrosis by downregulating tubular cell EMT." (PMID 41280890, 2025). "Whether dual GCGR/GLP-1R agonists confer protection against renal fibrosis remains unclear." (PMID 41280890, 2025). "In this study, we aimed to determine the efficacy of a novel GLP-1R and GCGR co-agonist, TB001 in the development of renal fibrosis using both in vitro and in vivo models." (PMID 41280890, 2025). "In summary, this study demonstrates that TB001, a novel GCGR/GLP-1R co-agonist, can effectively alleviate renal fibrosis in pre-clinical models, likely by attenuating PERK-mediated ER stress and EMT in tubular cells." (PMID 41280890, 2025). "This study demonstrated that TB001, a novel GCGR/GLP-1R co-agonist, effectively attenuates renal fibrosis in pre-clinical models, potentially through the inhibition of PERK-mediated ER stress in tubular cells." (PMID 41280890, 2025). "The mouse model of unilateral ureter obstruction (UUO) was used to determine the efficacy of the dual GCGR/GLP-1R agonist, TB001 in the protection of renal fibrosis." (PMID 41280890, 2025). "In this study, we aimed to investigate whether TB001, a novel dual GCGR/GLP-1R agonist, ameliorates renal fibrosis by inhibiting the PERK-mediated endoplasmic reticulum stress pathway, using well-established in vivo and in vitro models." (PMID 41280890, 2025). "In addition, other than the kidney cells, various other cell types in liver, pancreas, and blood vessels also expressed GLP-1R and GCGR; it cannot be ruled out that TB001 exerts its effect through these organs or cell types and indirectly prevents renal fibrosis." (PMID 41280890, 2025).
retinal degeneration (1 paper, 2016). Degeneration of the retina. "Diverse in vivo studies showed that chronic moderate hypoglycemia observed in glucagon receptor-deficient mice (Gcgr-/-) led to loss of vision and possible retinal degeneration, long-term exposure of this mouse model to carbohydrate diet normalized glycemia and partially restored retinal function." (PMID 26918849, 2016).
Sepsis (1 paper, 2021). Sepsis is defined as life-threatening organ dysfunction caused by a dysregulated host response to infection. "Based on these findings, it would be interesting to study new therapeutic strategies for sepsis, targeting GcgR, to reestablish the migration and activity of neutrophils and thus control bacterial infection in septic and diabetic patients." (PMID 34295325, 2021). "In addition, the GcgR antagonist improved diabetic mice survival rate without altering glycemia nor systemic inflammation induced by sepsis." (PMID 34295325, 2021).
metabolic disease (20 papers, 2019 to 2025). A congenital disorder (due to inherited enzyme abnormality) or acquired (due to failure of a metabolically important organ) disorder resulting from an abnormal metabolic process. "We investigated potential determinants of plasma proglucagon and associations of glucagon receptor signalling with metabolic diseases based on data from the UK Biobank." (PMID 38705923, 2024). "We therefore concluded that glucagon receptor agonism remains a promising candidate for metabolic disease treatment." (PMID 39236784, 2024). "Several multi-agonists with GLP-1 receptor (GLP-1R) and glucagon receptor (GCGR) activity are currently being developed to treat metabolic disease." (PMID 36384093, 2022). "Taken together, these data suggested that GCGR knockout in zebrafish induced metabolic disorder, especially in lipid metabolism and amino acid metabolism." (PMID 33520988, 2020). "The possibility of quantitative GCGR PET imaging will potentially assist in pharmaceutical development as well as improved understanding of the human GCGR signaling in healthy and metabolic disease." (PMID 30771019, 2019). "Recent drug development suggests agonists may be more promising against glucagon receptor dysregulation in metabolic disorders." (PMID 40280422, 2025). "Our work suggests that it is worth evaluating whether lipid-modifying treatments can increase effectiveness of therapeutic GCGR agonism in metabolic disease." (PMID 35718339, 2022). "Moreover, we summarized some of therapeutic efforts directed at manipulating GCGR signaling for the treatment of metabolic diseases." (PMID 31405212, 2019). "In the present work we extend these observations to GIPR and GCGR, members of the same class B GPCR family and major investigational targets for metabolic disease." (PMID 33268378, 2021). "To date, the majority of such agents being developed to treat metabolic diseases possess activity at the GLP-1R as the anchor pharmacophore but are also agonists for either the GIPR, the glucagon receptor, or both." (PMID 32730231, 2020). "The glucagon receptor (GCGR), GLP1R, and GIPR represent critical nodes in metabolic homeostasis, each contributing distinct physiological effects that collectively address the multifaceted nature of metabolic disorders." (PMID 41333850, 2025). "Indeed, the cross reaction of glucagon at the GLP-1R has proven to be vital for pancreas function and dual (or triple) agonists of the GCGR and GLP-1R (and GIP receptor) are currently being studied for the treatment of metabolic disorders." (PMID 36009454, 2022).